BRAF (B-Raf proto-oncogene, serine/threonine kinase)
Diseases named in the same sentence as BRAF in open-access papers (continued):
Sharing a sentence is not in itself a finding about the gene and the disease.
melanoma (continued). "Various BRAF mutations including BRAFV600E and BRAFS729A have been identified in cancer patients, such as lung adenocarcinoma and melanomas." (PMID 35585049, 2022). "At this point in time, limited data have been published concerning sequential treatment efficacy in patients with BRAF-mutant melanoma." (PMID 35565255, 2022). "To clarify the roles of AKT and BCL-2, we used AKT siRNA or navitoclax, respectively, the latter of which is a pro-apoptotic BH3-mimetic used in clinical trials for melanoma and other cancers, along with BRAF/MEK inhibition." (PMID 35216449, 2022). "The induction of ECM-related signaling pathways is a mechanism that is implored by melanoma cells to evade BRAF inhibition and confers tolerance and resistance to BRAF inhibitor treatment." (PMID 36119516, 2022). "Included in melanoma mol-GPA index, BRAF mutational status is closely related to the more aggressive behavior of melanoma in a metastatic setting and is a predictor for the choice of therapy." (PMID 36497248, 2022). "Exploiting the expression of melanogenesis-associated transcription factor target gene CYP27A1 and inhibiting mitochondrial OxPhos suggest a strategy for BRAF/NRAS mutant melanoma." (PMID 35311151, 2022). "Blocking PD-1H with a specific antagonist mAb can significantly reduce tumor growth in multiple mouse tumor models, including B16 melanoma, MB49 bladder carcinoma, and PTEN/BRAF inducible melanoma by promoting T cell–mediated immunity." (PMID 34905507, 2022). "Several efforts have been made to develop promising melanoma therapies, such as the combined target therapy against BRAF and Mitogen-Activated protein kinase (MEK) 12-14." (PMID 35371312, 2022). "The treatment strategy that shows good efficacy against BRAF altered melanomas (monotherapy with BRAF inhibitors vemurafenib, dabrafenib and encorafenib)." (PMID 35621644, 2022). "Another worrying result was seen in models of mice with BRAF V600E-positive melanoma whose KD exacerbated tumor growth." (PMID 36079756, 2022). "While dual inhibition of BRAF and MEK as a standard treatment for advanced BRAF-mutant melanoma showed a high response rate, the response duration for many patients is relatively short." (PMID 35806358, 2022). "The paradigm for treatment of late-stage melanoma has changed since the approval of checkpoint inhibitor immunotherapies and BRAF targeted therapies in 2011." (PMID 36358601, 2022). "Melanoma is often resistant to BRAF or MEK inhibitors (vemurafenib or trametinib, respectively) used in mono- or combination treatments." (PMID 35422482, 2022). "BRAF-resistant melanomas adapt to therapy by altering cytoskeletal gene expression, which leads to myosin II activity restoration." (PMID 36699013, 2022). "For example, VATG-027 and VATG-032 have therapeutic potential to sensitize oncogenic BRAF V600E mutant melanoma tumor to vemurafenib by lysosomal deacidification and disruption of autophagosome." (PMID 36034776, 2022). "It was serendipity that some studies had indicated that patients with melanoma were at reduced risk for development of AF when treated with BRAF and MEK inhibitors compared to patients treated with BRAF inhibitor monotherapy." (PMID 35911532, 2022). "Further studies should be performed to clarify the influence of miR-125b, miR-200c and miR-205 in the treatment of melanoma patients with BRAF inhibitors." (PMID 35326682, 2022). "Binimetinib (MEK162) is a potent and selective oral, adenosine triphosphate noncompetitive, small-molecule inhibitor of MEK1/2 approved for the treatment of BRAF mutant melanoma when given in combination with the BRAF inhibitor encorafenib." (PMID 37359242, 2022). "Mutations in the RAS and RAF family of oncogenes have been detected in a significant percentage (15 and 50%, respectively) of human melanoma patients, leading to the development of BRAF and MEK inhibitors as potential therapeutic agents." (PMID 36686160, 2022).
melanoma (continued). "Many oncologists favor immunotherapy for melanoma initially, perhaps since it is readily accessible and precludes the need for BRAF testing." (PMID 36589179, 2022). "For instance, KDM5B gene elimination sensitizes melanoma cells to BRAF blockage, despite the fact that survived cells display the IDTC phenotype." (PMID 36224606, 2022). "Anti-PD-1 ICI and BRAF-/MEK-inhibition with the dabrafenib plus trametinib (restricted to patients with BRAFV600-mutant melanoma) have become standard adjuvant treatment options that significantly improve RFS in patients with resectable stage III/IV disease." (PMID 35158952, 2022). "BRAF was initially found to be in 44-66% of melanomas in the general population, and that has since been corroborated with other reports in that range." (PMID 35712493, 2022). "In this study, we designed several chloroquine derivatives—2‐methyl‐7‐chloroquinoline and methylcarbazole hybrid compounds that have certain BRAF‐mutant melanoma inhibitory activities—and identified the most active compound, lj‐2‐66." (PMID 35332658, 2022). "Several mechanisms involve miRNA in the development of melanoma resistance to BRAF inhibitors (BRAFi) and MEK inhibitors (MEKi), which block the MAPK pathway; this limits their prolonged use." (PMID 36613640, 2022). "Studies have shown that endogenous RAC1P29S in BRAFV600E mutant melanoma is related to early resistance to BRAF inhibitors, and silencing RAC1P29S expression can restore the sensitivity of cells to BRAF inhibitors." (PMID 36387162, 2022). "A phase II study of encorafenib, binimetinib, and nivolumab versus ipilimumab and nivolumab in BRAF V600 mutant melanoma patients with brain and leptomeningeal metastases is also currently recruiting (NCT04511013)." (PMID 35790709, 2022). "Tumors with this variant are responsive to treatment with BRAF inhibitors (e.g., dabrafenib, vemurafenib) and in combination with MEK inhibitors this has been shown to be an effective treatment strategy for melanoma." (PMID 35525914, 2022). "Melanoma cells are strongly invasive and present strong resistance to clinical interventions, except for immunotherapy and BRAF-targeted therapy." (PMID 35847022, 2022). "Survival rates of real-world patients with advanced melanoma treated with BRAF-MEK are lower than in trial patients, which is possibly related to poorer characteristics with regard to age, LDH level and metastatic sites." (PMID 35703270, 2022). "Globally, our results showed that miR-125b, miR-200c and miR-205 expression predicted the clinical outcome of primary melanomas independently of BRAF status." (PMID 35326682, 2022). "Dabrafenib plus trametinib is also recommended as combined adjuvant therapy for 52 weeks after resection in IIIA/B/C/D BRAF-mutant (V600E/K*) melanomas." (PMID 36844955, 2022). "Mitogen-activated protein kinase (MEK) 1/2 are downstream targets of BRAF and drive oncogenesis in melanoma." (PMID 35626272, 2022). "Regarding ERβ, we observed comparable levels in primary melanomas and in NRAS mutated metastatic cell lines, and lower, but well detectable levels in the BRAF mutated primary Me1402/R and metastatic A375M cell lines." (PMID 35371312, 2022). "This sequencing technology has been used in melanoma research to unravel the clinical phenotypes related to NRAS and BRAF mutations." (PMID 36431075, 2022). "We further use the model to predict the changes in the metabolic and gene expression profiles of melanoma cells under treatment with a BRAF inhibitor that can suppress glutamine uptake." (PMID 35148308, 2022). "Of the 40 patients with BRAF V600E/K mutant melanoma, two patients declined adjuvant treatment, and one had a contraindication (severe liver cirrhosis)." (PMID 35336796, 2022).
melanoma (continued). "The main melanoma driving mutations are part of ERK pathway, with BRAF mutations being the most frequent ones, followed by NRAS, NF1 and MEK mutations." (PMID 35941108, 2022). "By specifically targeting V600E-mutated BRAF, Vem has shown appreciable antitumor activity, and improved survival rates in patients with BRAF V600E-mutant melanoma." (PMID 36034784, 2022). "Genetic alterations of either NRAS (15–20%) or BRAF (40–50%) arise early during melanoma pathogenesis and are preserved throughout tumor progression." (PMID 35580987, 2022). "MEK inhibitors (MEKi) are approved in BRAF mutated melanoma and NSCLC in combination with BRAF inhibitors." (PMID 35814409, 2022). "In melanoma, the inhibition of BRAF promotes the upregulation of FOXD3 (factor Forkhead box D3) by blocking MEK/ERK." (PMID 35831836, 2022). "In melanoma, the MAPK pathway can also be activated by mutations in BRaf (BRafv600E), while the PI3K pathway can be constitutively activated by mutations in its PI3K component." (PMID 35954497, 2022). "This miRNA was found to be down-regulated in BRAF-mutant melanoma cells and even more when they developed resistance to MAPKi." (PMID 36438490, 2022). "The Gold Standard BRAF V600E assessment in metastatic melanomas and papillary thyroid carcinomas is direct DNA sequencing." (PMID 35468886, 2022). "Combination HSV/BRAFi is an immunogenic therapy for BRAF mutant melanoma, but cannot fully control tumors." (PMID 35338089, 2022). "Key chemotherapeutic agents targeted for melanoma include inhibitors of the RAS-RAF-MEK pathway, particularly inhibitors of mutated BRAF (BRAFV600E) and MEK proteins." (PMID 36286442, 2022). "Our results indicate both ITF2357 and SAHA dose-dependently reduce the viability of BRAF-mutated SK-MEL-28 and A375 melanoma cells." (PMID 36009541, 2022). "The V600E change is easily the most frequent driver mutation in melanoma, especially in SSM, and it comprises up to 90% of all BRAF mutations in CMs, with V600K, V600R, and K601E making up most of the remaining 10%." (PMID 36143375, 2022). "We previously showed that in matched patients with BRAFV600-mutant advanced melanoma with relatively favorable characteristics, first-line anti-PD-1 monotherapy leads to an improved OS compared to first-line BRAF/MEK inhibition." (PMID 35703270, 2022). "Epigenetic rewiring integrates signals from multiple heterotypic intracellular networks and is therefore a key driver of melanoma resistance to the two mainstream therapeutic approaches: immunotherapy and BRAF inhibition." (PMID 35409020, 2022). "The BRAF oncogene promotes melanoma proliferation and metastasis by hyper-activating the ERK/MEK Mitogen-Activated Pathway (MAPK)." (PMID 35323214, 2022). "Studies have found that 70% of melanomas are associated with BRAF and NRAS gene mutations, so there are many studies on BRAF- and NRAS-mutant melanoma." (PMID 35310910, 2022). "For example, secretion of the MET ligand hepatocyte growth factor by tumor stromal fibroblasts confers resistance to BRAF V600E inhibitors and correlates with poor prognosis in melanoma." (PMID 36214609, 2022). "Subsequent investigation in BRAF WT melanoma cell lines indicated that DUSP4 depletion enhanced cell survival and decreased sensitivity to MEK inhibition." (PMID 36576731, 2022). "Researchers also found that inhibition of RSK2 by CF-X9, a RSK2 inhibitor discovered by virtual screening, hindered the cell growth in BRAF inhibitor-resistant melanoma cells." (PMID 36210843, 2022). "Further studies are yet needed to better understand the metabolic response of melanoma to BRAF/MEK inhibition in the YUMM1.7 model." (PMID 35327519, 2022). "During maturation, heterogeneous melanoma spheroids exhibited BRAF inhibitor resistance by producing tumor stromal niches." (PMID 36026581, 2022).
melanoma (continued). "A potential explanation is that patients with BRAF-mutant melanomas were administered BRAF and MEK inhibitor combination therapy or previous BRAF monotherapy (77.4% of the patients with BRAF mutations)." (PMID 35885042, 2022). "Future experiments should focus on paradox inhibitors, specifically in unresectable BRAF V600E-mutant melanoma, to better understand their therapeutic potential." (PMID 35954441, 2022). "Clinical therapies have been established with vemurafenib, a selective inhibitor of BRAF (v-raf murine sarcoma viral oncogene homolog B) and dabrafenib in treating malignant melanoma, as well as non-small cell bronchial and thyroid carcinoma." (PMID 34687436, 2022). "The STAT3 pathway is frequently upregulated in BRAF inhibitor resistant melanoma, which can drive invasion and metastasis." (PMID 36084109, 2022). "Binimetinib and cobimetinib are also FDA‐approved MEKi and are, like trametinib, indicated for BRAF+ melanoma." (PMID 34861096, 2022). "A recent study using A2058 cells, expressing the BRAF oncogenic mutation (BRAFV600E), showed that fucoxanthin from the haptophyte Tisochrysis lutea is able to restore melanoma cells sensitivity to BRAFi (vemurafenib) and alkylating (dacarbazine) agents." (PMID 36286442, 2022). "In this retrospective study, we performed MxIHC and subsequent whole-tumor imaging spatial analyses of tumors obtained from 11 melanoma patients prior to BRAF/MEK-targeted therapy and after the disease progressed." (PMID 35058553, 2022). "The results achieved by using a combined treatment with BRAF and MEK inhibitors led to a significant improvement in the progression-free survival (PFS) and overall survival (OS) of patients with BRAF-mutant advanced melanoma." (PMID 35335966, 2022). "The introduction of CPI and BRAF/MEK-inhibitors led to a significant advancement in melanoma therapy, and even profound tumor responses can be found in some patients with advanced melanoma." (PMID 35565212, 2022). "LL‐Z1640‐2 and patulin also induced apoptosis in BRAF inhibitor‐resistant melanoma, pancreatic cancer, cholangiocarcinoma and colorectal cancer cells." (PMID 36282887, 2022). "The blocking of this MAPK pathway activation by a combination of BRAF inhibitors and MEK inhibitors demonstrated significant clinical benefit in patients with BRAF V600-mutated melanomas." (PMID 35059911, 2022). "We then unravel the molecular mechanism by which SEMA6A regulates the remodeling of actin cytoskeleton thereby sustaining the aggressive behavior of BRAF-mut melanoma cells, and show the involvement of downstream RhoA-YAP cascade." (PMID 35440004, 2022). "Around 5–10% of advanced melanoma patients progress early on anti-BRAF targeted therapy and 20–30% respond only with the stabilization of the disease." (PMID 35565444, 2022). "Here, we examine how targeted therapy reprograms metabolism in BRAF-mutant melanoma cells using a genome-wide RNA interference (RNAi) screen and global gene expression profiling." (PMID 35232962, 2022). "This peculiar distribution among BRAF functional classes in NSCLC is in contrast with data from melanoma and thyroid carcinoma patients, where TERT mutations have been mainly described in BRAF V600E-mutant tumors." (PMID 35884534, 2022). "In the last 10 years, further indications were approved in different subsets of melanoma either as a monotherapy or as a combination therapy with nivolumab, like in B-Raf Proto-Oncogene (BRAF) V600 wild-type unresectable or metastatic melanoma." (PMID 35641998, 2022). "The expression of SEMA6A protein was higher in melanoma tissues from BRAF-mut patients than in melanoma tissues from BRAF-wt patients." (PMID 36601121, 2022). "As previously discussed, numerous combinations of BRAF/MEK inhibitors such as dabrafenib/trametinib and vemurafenib/cobimetinib, have proven to be more effective than BRAF inhibitors alone in treating BRAF V600 mutant melanoma." (PMID 35954441, 2022).
melanoma (continued). "One limitation resides in the fact that part of these melanoma samples received BRAF inhibitors (BRAFi) prior to ICB." (PMID 35432344, 2022). "Despite the evident importance of BRAF testing in the diagnosis, treatment, and prognosis of melanoma and CRC, there is a paucity of molecular data." (PMID 36589179, 2022). "Although BRAF inhibitors are effective treatments in BRAF mutant melanoma, this approach has been ineffective in colorectal cancer." (PMID 36230757, 2022). "Vemurafenib and, later, dabrafenib, elicited partial responses in most patients with metastatic BRAF-mutant melanoma, and some patients presented complete responses with impressive tumor shrinkage." (PMID 35234863, 2022). "Previous studies evidenced that treatment with inhibitors that target the BRAF kinase combined with anti-PD-1 therapy improved antitumor immunity in BRAF-mutant melanoma." (PMID 36159823, 2022). "The role of NF1 loss-of-function in the reactivation of the RAS/MAPK pathway upon BRAF inhibition was confirmed in multiple other melanoma cell lines and in an Nf1-knockout mouse model." (PMID 35234863, 2022). "The ArcherDX custom melanoma ctDNA panel detected 13/17 (76%) patients with BRAF- or NRAS-mutant melanoma." (PMID 35494035, 2022). "Particularly, the combination of BRAF and MEK inhibitors has improved overall survival in BRAF-mutated advanced melanoma and is now approved as a first-line therapy." (PMID 36230620, 2022). "Multiple FDA-approved kinase inhibitors currently in use for melanoma include a combination of the MEK inhibitor (MEKi) trametinib (GSK1120212) and BRAF inhibitor dabrafenib for BRAFV600 mutations." (PMID 35216449, 2022). "Its overexpression is related to both intrinsic and acquired resistance of melanoma cells to BRAF/MEK inhibitors." (PMID 35565444, 2022). "Taken together, these findings suggest that pre-treatment PD-L1+ PMN frequencies selectively predict patient clinical outcome and therapeutic response to nivolumab only in BRAF wild type melanoma patients." (PMID 36016960, 2022). "CCT196969 has been shown to target mutated BRAF, CRAF and SFKs in BRAF-mutated primary melanoma cell lines, resulting in decreased expression levels of p-MEK and p-ERK." (PMID 36084109, 2022). "We see great responses in KRAS-driven lung cancer, but hardly any in colorectal cancer, which mirrors the BRAF-driven melanoma versus colorectal cancer differences." (PMID 34498671, 2022). "Treatment for melanoma has dramatically changed over the past decade with the introduction of immune checkpoint inhibitors and BRAF, plus MEK-targeted therapies into clinical practice." (PMID 36497340, 2022). "Expression levels of miR-125b, miR-200c and miR-205 were significantly lower in BRAF WT primary tumors of patients who died from melanoma (p-value 0.0025, 0.0004 and 0.0008, respectively)." (PMID 35326682, 2022). "In murine models and human samples of BRAF-mutant melanoma, tumors induced the accumulation of regulatory T cells (Treg), which limited effector T cell activity." (PMID 36016960, 2022). "Under a treatment regime for melanoma (BRAF/MEK inhibitors) and combined stereotactic radiation, the disease was stable for 3 years." (PMID 35198980, 2022). "Perhaps the best example has been the rapid development of BRAF inhibitors (BRAFi, such as vemurafenib and dabrafenib) for the treatment of melanoma." (PMID 35903549, 2022). "BRAF/MEKi combinations, including dabrafenib/trametinib, vemurafenib/cobimetinib and encorafenib/binimetinib, are associated with high objective response rates (ORRs), in the order of 70%, for advanced BRAF-mutant melanoma." (PMID 35366166, 2022). "The adaptive response of melanoma cells to BRAF inhibition implicates force‐induced actomyosin cytoskeletal remodeling." (PMID 34957688, 2022). "Triple therapy for BRAF-mutant patients: the standard of care for BRAF-mutant melanoma patients is either BRAF/MEK inhibitor therapy or immunotherapy." (PMID 36232957, 2022).